E2F1 (E2F transcription factor 1)
Diseases named in the same sentence as E2F1 in open-access papers (continued):
Sharing a sentence is not in itself a finding about the gene and the disease.
diabetes (17 papers, 2008 to 2024). "Instead, E2f1/2-deficient mice are more likely to have increased polyploidy, diabetes, and exocrine pancreas dysfunction." (PMID 37526344, 2023). "Previous studies demonstrated that mice with loss of both E2f1/2 developed marked enhanced pancreatic polyploidization, diabetes and exocrine pancreas insufficiency." (PMID 29329320, 2018). "Increased microRNA-330 and decreased E2F1 mRNA expressions were observed to be associated in T2DM patients and were found to be linked with various diabetes risk factors." (PMID 32884568, 2020). "Alterations in glucose metabolism have been previously linked to the E2F/Rb pathway as demonstrated by double knock-out of E2F1/E2F2 which impaired insulin production and caused diabetes." (PMID 28085920, 2017). "Genetic ablation of Cdk4 activity, cyclin D2, or combined E2f1 and E2f2, results in defective maintenance of adult pancreatic β-cells, eventually resulting in severe diabetes." (PMID 20090907, 2010). "PDK4 expression has been shown to be regulated by various metabolic stimuli (such as starvation, exercise, and diabetes), the transcription factors FOXO and E2F1, and epigenetic mechanisms such as promoter methylation and histone acetylation." (PMID 25379179, 2014). "E2f1, Sox10 and SP1 were found to likely regulate the expression of genes found only in diabetes." (PMID 38039846, 2024). "Our results suggest that inhibition of endogenous E2F1 may serve as an alternative approach to ensure continuous expression of VEGF in the wound and this is particularly useful for certain pathological conditions (e.g., diabetes), in which hypoxic response and VEGF induction are impaired." (PMID 27490344, 2016).
pituitary tumor (12 papers, 2015 to 2024). A benign or malignant neoplasm affecting the pituitary gland. "The overexpressed EGFR and E2F transcription factor 1 (E2F1) were implicated in the aggressiveness of pituitary tumors." (PMID 35528020, 2022). "Moreover, this study underlines E2F1 increased activity and, then, cell cycle disturbances as critical features of pituitary tumors development also in ACTH tumors, as already largely evidenced in other histotypes." (PMID 31487906, 2019). "This displacement leads to increased acetylation of both E2F1 and histones at E2F1 target gene sites, ultimately promoting cell cycle progression in pituitary tumors." (PMID 39085703, 2024). "Several genes involved in aggressive PRL pituitary tumors have been shown to be under the transcriptional regulation of E2 transcription factor 1 (E2F1), which in turn is regulated by MYC and some miRNAs." (PMID 34564317, 2021). "In conclusion, they suggest miR-17-5p and E2F1 as promising biomarkers of proliferation and invasiveness of pituitary tumors, respectively, thus helping the clinical management of PitNETs." (PMID 34564317, 2021). "Overall, they assumed that E2F1 and miR-17-5p could be promising good biomarkers of invasiveness and proliferation, respectively, thus helping the clinical management of pituitary tumors." (PMID 33066578, 2020). "Therefore, the results obtained by the analysis of the corti-EGFR-Tg mouse model support previous findings indicating that EGFR1 activity is mediated by E2F1 and EGFR1 overexpression is associated with aggressive pituitary tumors." (PMID 31487906, 2019). "Furthermore, it was shown that hPTTG1 may act as a direct E2F1 target, and both were concordantly overexpressed in Rb+/− murine pituitary tissues and human pituitary tumors." (PMID 35033090, 2022). "As all non-functioning PitNETs (GTs and sCTs) were macroadenomas, while some functioning PitNETs (fCTs and STs) were microadenomas, the effect of E2F1 on the growth and invasiveness of pituitary tumours could be mediated by its interaction with MYC and miR-17-5p." (PMID 32316225, 2020). "Although EGFR is expressed in other lineages of aggressive pituitary tumors, our findings suggest that EGFR signaling induces E2F1-mediated POMC transcription and corticotroph adenoma pathogenesis." (PMID 30147673, 2018).
renal cell carcinoma (12 papers, 2016 to 2024). "Previous study reported that transcriptional inhibition of E2F1 inhibits renal cell carcinoma progression." (PMID 38783241, 2024). "This study aims to clarify the mechanistic action of long non-coding RNA (lncRNA) SNHG12 in the development of renal cell carcinoma (RCC), which may be associated with promoter methylation modification by KMT2B and the regulation of the E2F1/CEP55 axis." (PMID 35597996, 2022). "The circSDHC / miR-127-3p / CDKN3 / E2F1 axis promotes renal cell carcinoma progression." (PMID 34716323, 2021). "The suppression of the E2F1 pathway could be prevented by circSDHC binding competitively to miR-127-3p, thereby leading to renal cell carcinoma (RCC) malignant progression." (PMID 34262589, 2021). "Similarly, the E2F1 gene has been suggested as a potential therapeutic target and highlighted as playing a key role in renal cell carcinoma." (PMID 28178311, 2017). "CircRNA also plays an important role in the development of renal cell carcinoma (RCC) by regulating CDKN3/E2F1 in combination with miR-127-3p." (PMID 36138829, 2022). "In renal cell carcinomas (RCC), PAX8 promotes tumor growth through regulation of the E2F1-RB pathway." (PMID 27129161, 2016). "Additionally, Nic prohibits the expression of C-MYC and E2F1, while inducing the expression of PTEN in renal cell carcinoma (RCC)." (PMID 35457127, 2022).
lung squamous cell carcinoma (11 papers, 2012 to 2025). "Sun and colleagues have indicated that the levels of E2F1 and E2F3 expression were increased in LUAD and lung squamous cell carcinoma (LUSC) tissues." (PMID 40070576, 2025). "However, squamous cell lung carcinoma cases have no prognostic impact of E2F1." (PMID 26601052, 2015).
medulloblastoma (11 papers, 2008 to 2023). A malignant, invasive embryonal neoplasm arising from the cerebellum. "This firmly linked E2F1 activity downstream of Shh to de novo lipid synthesis in medulloblastoma and their proposed cells-of-origins." (PMID 22407012, 2012). "Shh-associated medulloblastomas share many characteristics of these cerebellar granule neuron precursors (CGNPs), including high expression of N-myc, microRNA miR 17/92, increased lipogenesis, and as we previously reported and show again here elevated E2F1." (PMID 22407012, 2012). "Taken together, the results of our in vivo analysis and in vitro manipulation of E2F1 indicate that in Shh-associated mouse medulloblastomas and in proliferating CGNPs, glycolysis is elevated in an E2F1-dependent manner and its regulation functionally lie downstream of PPARγ." (PMID 22407012, 2012). "A recent report showed that in glial cells of transgenic mice, overexpression of E2F1, a transcription factor downstream of rb1 pathway, also resulted in the induction of medulloblastomas and other PNETs." (PMID 28903419, 2017). "Treatment of medulloblastoma cells with JQ1 potently suppressed E2F1 activity compared to control treated cells as measured by a E2F1 responsive luciferase reporter." (PMID 24796395, 2014). "In this study, we show that in medulloblastoma and CGNPs, the Shh pathway is coupled—through E2F1—to the steroid receptor PPARγ and the control of glycolysis, a vital cellular process." (PMID 22407012, 2012). "This also reveals a dominant role of Shh in the etiology of glucose metabolism in medulloblastoma and underscores the function of the Shh → E2F1 → PPARγ axis in altering substrate utilization patterns in brain cancers in favor of tumor growth." (PMID 22407012, 2012). "Additionally JQ1 also promotes senescence in medulloblastoma cells by activating cell cycle kinase inhibitors and inhibiting activity of E2F1." (PMID 24796395, 2014). "Indeed, our data implicate this E2F1-dependent glycolytic process as a systematic, distinctly cell-autonomous process that is mediated by PPARγ but triggered by Shh in medulloblastoma." (PMID 22407012, 2012). "The requirement for E2F1 in Shh-regulated PPARγ dependent-glycolysis, as demonstrated, highlights its engagement in metabolic core fluxes and underscores the critical role for the Rb/E2F complex in metabolic reprogramming of medulloblastomas and their cells-of-origin." (PMID 22407012, 2012). "According to the Cavalli dataset, the high expression of E2F1, E2F2 and E2F8 correlates with poor prognostic outcomes in medulloblastoma patients." (PMID 35011618, 2021). "Oliver’s team in research performed on a mouse model of medulloblastoma showed that MYCN promotes cell cycle gene expression; increase of MYCN expression level was there reported with significantly increased levels of E2F1 (3.7-fold), and E2F2 (6.1-fold)." (PMID 33430425, 2021). "MiR-193a not only targeted MAX but several proliferation-related genes like CCND1, E2F1, STMN1, and chromatin modifier gene KMT2A that brought about widespread repression of gene expression in the MYC amplified Group 3 medulloblastoma cells." (PMID 32410663, 2020). "The decrease in the expression levels of proliferation-related targets of miR-193a like E2F1, CCND1, and several other cell cycle regulators like CDK2, CCND2 is consistent with the growth inhibition of medulloblastoma cells upon the expression of miR-193a." (PMID 32410663, 2020). "We next examined whether in medulloblastomas expression of PPARγ, like that of FASN, requires E2F1 activity." (PMID 22407012, 2012). "In more recent work, we demonstrated that excessive mitogenic signaling by Shh, a driver of medulloblastoma, engages the Rb/E2F tumor suppressor complex, activates the key enzyme fatty acid synthase (FASN) and drives lipogenesis through a novel, E2F1-regulated process." (PMID 22407012, 2012).
acute myeloid leukemia (10 papers, 2013 to 2025). Acute myeloid leukemia (AML) is a group of neoplasms arising from precursor cells committed to the myeloid cell-line differentiation. "It has been proved that the transcription factor E2F1 binds and represses miR-223 promoter in human acute myeloid leukemia (AML) and that miR-223 promoter regulation is conserved among human and mouse." (PMID 24727437, 2014). "For instance, hsa-miR-100, which is highly expressed in the p16INK4a wild-type cell lines, targets the RBSP3 gene that in acute myeloid leukemia regulates the cell cycle through partial modulation of pRB/E2F1." (PMID 23601657, 2013). "Besides, miR-223 which formed a feedback loop with the cell cycle regulator gene E2F1 was found to be underexpressed in acute myeloid leukemia (AML)." (PMID 33842368, 2021). "C/EBPα-p30, a mutant of transcription factor C/EBPα, which was found in around 9% of acute myeloid leukemia (AML) patients, induces Pin1 expression by recruiting E2F1 in the PIN1 promoter and enhances leukemia." (PMID 32296699, 2020). "For example, E2F1-regulated miRNAs function as tumor suppressors to arrest cell-cycle and induce apoptosis, and E2F1-miR-223 negative feedback loop plays a role in acute myeloid leukemia." (PMID 27153550, 2016). "In hematological malignancies, TRIB2 as a target gene of MEIS1, E2F1, and NOTCH1 participates in acute myeloid leukemia (AML) and T cell acute lymphoblastic leukemia (T-ALL)." (PMID 33794905, 2021).
head and neck squamous cell carcinoma (10 papers, 2012 to 2025). A squamous cell carcinoma that arises from any of the following anatomic sites: lip and oral cavity, nasal cavity, paranasal sinuses, pharynx, larynx, and salivary glands. "PSMD14 overcame drug resistance in head and neck squamous cell carcinoma by inhibiting E2F1 ubiquitination and degradation, improving Akt pathway activation and SOX2 transcription." (PMID 37349676, 2023). "A study of head and neck squamous cell carcinoma revealed that miR‐618 participated in cancer progression by regulating the E2F1 and SMAD genes expression." (PMID 34848810, 2021). "In head and neck squamous cell carcinoma, PSMD14 can influence tumor cell proliferation, drug resistance, and cell stemness by blocking E2F1 ubiquitination and degradation, boosting Akt pathway activation, and promoting SOX2 transcription." (PMID 38053170, 2023). "The possible linkage between E2F1 and the PI3K/AKT signaling has been recently appreciated in head and neck squamous cell carcinoma." (PMID 34699320, 2021). "Similarly, in head and neck squamous cell carcinoma (HNSCC), PSMD14 decreased E2F1 ubiquitination and degradation, which improved AKT pathway activation and SOX2 transcription, thereby facilitating HNSCC growth, chemoresistance, and stemness." (PMID 36959615, 2023).
small cell lung carcinoma (10 papers, 2009 to 2022). Small cell lung cancer (SCLC) is a highly aggressive malignant neoplasm, accounting for 10-15% of lung cancer cases, characterized byrapid growth, and early metastasis. "A recent study showed that E2F1 is closely associated with EMT in small cell lung cancer." (PMID 32010624, 2019). "It was also shown that E2F transcription factor 1 (E2F1) drives ADAM12 expression in small cell lung cancer cells." (PMID 35610640, 2022). "It's worth noting that E2F1 and CCNE1 had high MCODE score in DMDD targets PPI and both of them were demonstrated to be associated with cell cycle and pathways in cancer and small cell lung cancer." (PMID 33613291, 2021). "High expression of E2F-1 also has been shown in small cell lung cancer, and these tumors do not express Hes-1." (PMID 19891787, 2009). "E2F1 corticotroph specificity also seems to be subclass specific: E2F1 but not E2F3 enhanced POMC promoter activities by deletion mutant hPOMC luciferase assays using ectopic ACTH-secreting tumor cells derived from human small cell lung cancer DMS79 cells." (PMID 30147673, 2018).
thyroid cancer (10 papers, 2017 to 2025). "We compared the expression levels of E2F1 between normal thyroid cells (Nthy-ori-3-1) and thyroid cancer cells (TPC-1 and K1) via PCR." (PMID 41050059, 2025). "In this study, biological information analysis identified four genes, HSPA6, FLNC, CLDN2, and E2F1 as candidate biomarkers of thyroid cancer." (PMID 37063290, 2023). "Previous in vitro studies demonstrated that E2F1 has a tumor-promoting effect in lung, breast, and thyroid cancers." (PMID 34299042, 2021). "Furthermore, canagliflozin inhibited G1/S phase transition and cyclin D1, cyclin D3, cyclin E1, cyclin E2, and E2F1 expression levels in thyroid cancer cell." (PMID 35148777, 2022). "In human thyroid cancer cells, SLC26A4-AS1 silencing enhances the interaction between DDX5 and the transcription factor E2F1; then, the DDX5-E2F1 complex binds to the MRN gene promoter and thus stimulates the MRN/ATM-dependent DNA DSB signaling cascade and thyroid cancer metastasis." (PMID 35992805, 2022).
clear cell renal cell carcinoma (9 papers, 2013 to 2025). "In clear cell renal cell carcinoma (ccRCC) patients, high levels of E2F transcription factor 1 (E2F1) and SREBP-1 are associated with poor prognosis." (PMID 35912181, 2022). "E2F1 can increase the proliferation and metastasis of clear cell renal cell carcinoma (ccRCC) through SREBP1-induced aberrant lipid metabolism." (PMID 36414640, 2022). "Additionally, it was reported that E2F1 promotes the proliferation and metastasis of clear cell renal cell carcinoma by activating SREBP1-dependent fatty acid biosynthesis." (PMID 41155666, 2025). "E2F1 plays a vital role in cell proliferation, it is unclear whether lncRNA H19 has effects on proliferation of clear cell renal cell carcinoma cells." (PMID 29214011, 2017). "Transcription factor E2F1 was mainly distributed in cancer cell nucleus and mRNA expression significantly increased in 72 cases of clear cell renal cell carcinoma (ccRCC) tissues compared with adjacent non-cancerous kidney tissues (p<0.001)." (PMID 24023875, 2013).
esophageal squamous cell carcinoma (9 papers, 2014 to 2025). Esophageal squamous cell carcinoma (ESCC) is a type of esophageal carcinoma (EC) that can affect any part of the esophagus, but is usually located in the upper or middle third. "E2F1 was highly expressed in esophageal squamous cell carcinoma (ESCC) cases and associated lymph node metastasis." (PMID 39119602, 2024). "Another study has shown that ZNF282 is a co-activator of E2F1 in esophageal squamous cell carcinoma and promotes tumor progression." (PMID 41331125, 2025). "Here, we focused on the relevance of E2F1 to esophageal squamous cell carcinoma (ESCC) and identification of E2F1-mediated network in this study." (PMID 34699320, 2021). "E2F1 appears to play different regulatory roles in human malignancies; E2F1 shows tumor-suppressing activity in esophageal, gastric, and colorectal adenocarcinoma, whereas it may function as a tumor promoter in pancreatic ductal adenocarcinoma and esophageal squamous cell carcinoma." (PMID 27175585, 2016). "Mechanistically, ZNF282 functions as a critical coactivator of E2F transcription factor 1(E2F1), transcriptionally upregulating the expression of cyclin A1 (CCNA1) and cell division cycle 6 (CDC6), thereby driving malignant progression in esophageal squamous cell carcinoma (ESCC)." (PMID 41331125, 2025).
Hepatic steatosis (9 papers, 2015 to 2023). Steatosis is a term used to denote lipid accumulation within hepatocytes. "As an example, in db/db leptin-deficient mice, E2f1 knockout was found to prevent hepatic steatosis through crosstalk with key metabolic pathways." (PMID 32701508, 2020). "In hepatocytes, up-regulated E2F1 drives lipid accumulation and gluconeogenesis, thus, promoting hepatic steatosis and systemic hyperglycemia." (PMID 36231008, 2022). "For example, E2F-1 (E2F transcription factor 1), a mediator of sustained lipogenesis and contributor to hepatic steatosis, was enriched positively in Ikbkg LKO and Rbpj LKO, and negatively in Glmp KO, coinciding with histological findings." (PMID 33467660, 2021). "E2F1, a transcription factor, contributes to the development of liver pathology due to its regulatory role in lipid synthesis and glycolysis while its deletion has been shown to abrogate hepatic steatosis in a murine model of NAFLD." (PMID 36777627, 2023). "Additionally, E2F1 deletion has been shown to abrogate hepatic steatosis in different mouse models of NAFLD." (PMID 36777627, 2023).
myeloma (9 papers, 2012 to 2024). "Knockdown of miR-551b caused increased TTP, led to less Cyclin D1 and E2F1 level, resulting in decreased myeloma proliferation and enhanced Dex sensitivity." (PMID 34983615, 2022). "ZFP36 encodes an RNA-binding protein, TTP, which downregulates two key factors in myeloma growth and proliferation - CyclinD1 and E2F1." (PMID 34983615, 2022). "Overexpression of E2F1 has been detected in mantle cell lymphoma and multiple myeloma, which closely related to the up-regulation of Cyclin D1." (PMID 29108247, 2017). "The authors postulated that overexpression of E2F1 may result in downstream gene programming that confers a proliferative advantage in myeloma cells, and that E2F1 overexpression can be used as a marker of selinexor resistance." (PMID 39050883, 2024). "Curiously, trabectedin treatment seems to upregulate E2F1 in multiple myeloma, which supports the hypothesis that the HMGA1/E2F1 axis could be activated as a mechanism of resistance after trabectedin." (PMID 38758230, 2024). "However, a study performed in non-hyperdiploid multiple myeloma proposed that ESR1 contributes to cell cycle dysregulation, thus affecting the transcription of several downstream genes including E2F1." (PMID 28806978, 2017).